PDPN (podoplanin)
Diseases named in the same sentence as PDPN in open-access papers (continued):
Sharing a sentence is not in itself a finding about the gene and the disease.
tumor (continued). "Among the infiltrative tumor lesions, some tumor cells showed PDPN - expression while others showed PDPN + expression; even among those with PDPN + expression, basal layers with complete PDPN expression around the cancer nests was still lacking." (PMID 28086225, 2017). "Genes up-regulated in cells from tumor specimens grown under CRC culture conditions are enriched with markers for lung basal cells such as TP63 (> 60 fold), podoplanin (PDPN, > 36 fold), cytokeratin genes KRT6A (> 729 fold), KRT6B (> 98 fold), and adhesion molecules LGALS7B (> 200 fold)." (PMID 28052041, 2017). "Targeting CLEC-2 on platelets rather than podoplanin on tumor requires a care for platelet function in hemostasis." (PMID 28674748, 2017). "Since CCL21 was found to interact with PDPN the regulation of both molecules may control the entry of CCR7+NK cells and their cytotoxicity in the tumor." (PMID 28416768, 2017). "Interaction between podoplanin and CLEC-2 may regulate tumor invasion and metastasis and might be a potential target for therapy of metastasis." (PMID 27564117, 2016). "VEGF and podoplanin (PDPN) have been identified as angiogenesis and/or lymphangiogenesis regulators and might be essential to restrict tumor growth, progression, and metastasis." (PMID 27313335, 2016). "Subsequent analyses of OSCC specimens demonstrated that PDGFRβ was abundantly expressed in stromal fibroblasts, while it was absent in tumor cells, with greater specificity compared to other markers such as αSMA or podoplanin." (PMID 27128408, 2016). "Regarding podoplanin, U87 tumors in vivo displayed only a few positive cells and for both T78 and T87 no podoplanin expression was found in tumor cells in any of the three models." (PMID 27454178, 2016). "Podoplanin expression was absent in tumor nests and was found only in the basal cell layer, with diffuse and extensive expression in the cytoplasm of the tumor cells." (PMID 26622791, 2015). "The anti-PDPN antibodies NZ-1 and NZ-8 induced antibody-dependent cellular cytotoxicity and complement-dependent cytotoxicity in eliminating cancer cells and suppressing TCIPA, tumor growth and tumor metastases." (PMID 26528756, 2015). "In contrast, the parental C6/LG cells did not express PDPN and were not able to induce platelet aggregation and form tumor cell-platelet aggregates." (PMID 26528756, 2015). "In this study, we did not seek to minimize the importance of the PDPN-CLEC-2 interaction for the tumor development and cancer metastasis." (PMID 26416352, 2015). "Thus CAFs expressing PDPN inhibit growth of SCLC cells, suggesting that CAFs expressing PDPN represent a tumor inhibitory stromal cell component in SCLC." (PMID 25909164, 2015). "PDPN enhances metastatic foci formation and tumor progression without affecting tumor growth in animal studies." (PMID 26528756, 2015). "The expression of podoplanin in CAFs did not correlate with the VEGF-A or VEGF-D expression in tumor cells." (PMID 25254213, 2014). "Our observation corresponded with the previous studies, showing by IHC method that in the majority of PTC cases PDPN is expressed in tumor cells, whereas FTC, FA and normal thyroid did not express podoplanin." (PMID 24797369, 2014). "We did not observe any statistically significant correlation in podoplanin expression between the samples from different tumor stages." (PMID 24797369, 2014). "Podoplanin neoexpression in PTC cases was not related to the tumor size or conventional vs FvPTC histological/morphological tumor subtype." (PMID 24797369, 2014). "Cytoplasmic PDPN expression was not statistically significantly different between patients with larger or smaller tumor size (pT) or histological (FvPTC vs classic PTC) subtype." (PMID 24797369, 2014). "This is an area that warrants further exploration, given that in vivo, many PDPN+ cells will be exposed to CLEC-2 signals, whether they are tumor cells interacting with CLEC-2+ platelets or FRCs interacting with CLEC-2+ DCs." (PMID 22988448, 2012).
tumor (continued). "Eight of these immune response genes (SPP1, PDPN, IL1RN, IL6, CCL8, MDK, IRF7, and HRH4) were expressed between 1.25–1.59 fold higher in the microglia/macrophage enriched population compared to bulk tumor." (PMID 22937035, 2012). "Among the 40 tumors analyzed, 9 (22.5%) did not demonstrate podoplanin expression and 18 (45%) had <10% positive tumor cells, which were considered to have low expression." (PMID 22580922, 2012). "In addition, tumor cells from MASL treated animals appeared more epithelial in nature, with a relatively flattened morphology and more restricted PDPN staining than tumors from untreated animals." (PMID 22844530, 2012). "More recently, it was reported that podoplanin, a plasma membrane glycoprotein, induces tumor cell migration and invasion without disrupting E-cadherin-mediated cell-cell junction both in vitro and in a transgenic model of carcinogenesis in vivo." (PMID 21526198, 2011). "Using EBC-1 cells, a lung SCC cell line without podoplanin expression and with lymphogenous metastatic potential, stable transformants with or without an exogenous human podoplanin gene were established and applied to a mouse tumor implantation model." (PMID 21034514, 2010). "As expected podoplanin was highly expressed in lymphatic endothelial cells, whereas in histologically normal squamous epithelium adjacent to the tumours podoplanin expression was not detectable or extremely low in some basal cells." (PMID 20196862, 2010). "Its involvement in tumour metastasis, however, has been demonstrated in an experimental model to be due to its platelet aggregation-inducing activity leading to pulmonary retention of CHO cells that overexpress podoplanin." (PMID 20196862, 2010). "Two (4%) of the tumours showed no podoplanin expression, 31 (58%) had weak or moderate expression (IRS scores 1-6), and 20 (38%) had high expression (scores 7-15)." (PMID 20196862, 2010). "Focal expression of podoplanin in the invading front but not in the tumour bulk was present in 59% of the samples, whereas diffuse expression was found in 12% of the cases investigated." (PMID 17179989, 2007). "As for PDPN targeting, the relief of the inhibitory signal delivered through the CD47-SIRP-α binding on macrophages could generate a pro-inflammatory TME favoring the anti-MB immune response, as indicated for other tumor types." (PMID 40677711, 2025). "The druggability of PDPN, PRSS3, GREM1, and LGALS1, alongside the established relevance of FAP, provides multiple entry points for stromal-directed interventions that could complement tumor cell–targeted therapies." (PMID 41198614, 2025). "Interestingly, further staining of these tumor sections with CAF-specific marker Podoplanin demonstrated that none of the tdTomato-labeled pericytes were positive for Podoplanin, including those pericytes detached from blood vessels." (PMID 38528180, 2024). "In the human PDAC patient tumor transcriptome (TCGA), we identify strong and significant correlations between tumoral GHR expression and known lymphangiogenic (LYVE1, FLT4, VEGFC, and PDPN) and angiogenic (PDGFRa, FGFR1, TGFB3, TGFB1, TGFBR2, HIF1a, IL6, and IL1B) markers." (PMID 39000545, 2024). "Additionally, the proportion of lymphatic ECs expressing PDPN was markedly increased in naïve tumor and its retention in non-pCR group correlated with poor response to neoICT." (PMID 39334513, 2024). "Since PDPN plays an essential role in normal cells such as kidney podocytes, lymphatic endothelial cells, and lung alveolar epithelial type I cells, anti-PDPN mAbs that recognize tumor cell-expressed PDPN but not normal cell-expressed PDPN have been desired for tumor therapy." (PMID 39594582, 2024). "Furthermore, high PDPN expression and increased risk of VTE were co-related, independent of age, sex, and tumor type." (PMID 39682237, 2024).
tumor (continued). "Taken together, our data identify CD142 and podoplanin as potential surface markers that are differentially expressed between cells with mutant, active beta-catenin and nonmutant, inactive beta-catenin in heterogeneous desmoid tumor samples." (PMID 37377751, 2023). "In contrast, we found that FAP and PDPN were specifically expressed in fibroblasts in tumor tissues but almost absent in normal tissues, indicating that they could be used as CAFs specific markers in various cancer types." (PMID 36744260, 2023). "However, tumor progression occurs independently of PDPN, and the blocking of PDPN does not represent a promising anti-cancer therapeutic approach." (PMID 38067218, 2023). "In the present study, the immunoexpression of PDPN was statistically significant in relation to the percentage of positive cells, staining intensity, IRS classification, and location of staining within the epithelium, tumor islands, and cells, as well as MLVD among all the groups." (PMID 37273383, 2023). "However, chemically-induced tumor development does not decrease in mice with a specific podoplanin deletion in the epidermal keratinocytes, indicating that podoplanin is dispensable in skin carcinogenesis." (PMID 35163233, 2022). "Furthermore, although podoplanin has been implicated in pathological lymphangiogenesis via interaction with galectin-8, we found no obvious effects on tumor-induced LN lymphangiogenesis in mice lacking lymphatic podoplanin expression." (PMID 35892863, 2022). "Thus, podoplanin can help stratify patients for elective neck dissection selection in early tumor stages and clinically negative nodal disease." (PMID 36247509, 2022). "Interestingly, 5 existing markers (ACTA2, VIM, S100A4, POSTN, PDPN) are not specific for any of the 9 tumor types we studied." (PMID 36263012, 2022). "There was no significant statistical correlation with podoplanin expression and tumor site." (PMID 36247509, 2022). "Furthermore, PDPN-positive cells showed a higher tumor-initiating potential than PDPN-negative cells." (PMID 35159384, 2022). "Differential gene expression analysis by Seurat34,35 identified 160 genes uniquely upregulated in tumor cells compared with TAF and normal kidney, including genes previously reported (e.g., GPNMB8, SQSTM1/p6236, MMP237, PTGDS38) and genes involved in tumor metastasis (e.g. MMP11, MDK, DCN, PDPN)." (PMID 36028490, 2022). "Podoplanin on tumor cells could mediate platelet aggregation via binding to CLEC2 on platelets and induce TGFβ release from platelets, facilitating EMT and extravasation of tumor cells." (PMID 34722319, 2021). "CAFs with high expression of podoplanin can also secrete a large number of cytokines and chemokines, such as TGF-β, tumor necrosis factor-α (TNF-α), interleukin-8 (IL-8), vascular endothelial growth factor (VEGF), which may promote tumor progression." (PMID 34566887, 2021). "PDPN, PDGFRβ, and αSMA behave similarly and all decrease over time in both tumour types, while the newest CAF marker, CD26, stands out as the only marker with intriguing opposite dynamics over time when comparing the two different tumours: increasing in the aggressive 4T1 while decreasing in 4T07." (PMID 34016130, 2021). "The tumours were analysed via flow cytometry for the simultaneous expression of six CAF markers: alpha smooth muscle actin (αSMA), fibroblast activation protein alpha (FAPα), platelet derived growth factor receptor alpha and beta (PDGFRα and PDGFRβ), CD26/DPP4 and podoplanin (PDPN)." (PMID 34016130, 2021). "In contrast, knockdown of podoplanin (PDPN) transmembrane protein does not affect tumor growth." (PMID 34571991, 2021). "Exhausted T cells from chronic infection however are not affected by IL-27 signaling and thus PROCR and PDPN expression may depend on the tumor microenvironment and not characterize all exhausted CTL." (PMID 32579593, 2020).
tumor (continued). "The limitations of the study were the small sample, the use of TMA acquired in commercial format where there is no certainty that the sections obtained are representative of the original biopsy and the lack of functional tests confirming that CAFs induce tumor expression of PDPN." (PMID 31967978, 2020). "However, other studies have demonstrated that forced PDPN expression stimulates tumor cell migration/invasion as clusters without inducing EMT (collective cell migration)." (PMID 32581653, 2020). "To perform clinical trials using spontaneously occurring canine tumor models, we developed a cancer-specific anti-canine PDPN (dPDPN) monoclonal antibody (mAb), PMab-38, which recognizes only dPDPN expression in canine tumor tissues without recognizing normal canine tissues." (PMID 33238582, 2020). "In addition, these authors used a transgenic mouse model of pancreatic cancer to show that podoplanin promotes tumor invasion without affecting tight junctions and E-cadherin-mediated cell–cell contacts." (PMID 30736372, 2019). "Furthermore, we observed a reduced CD4+/CD8+ ratio of tumor infiltrating lymphocytes in the absence of PDPN+ myeloid cells." (PMID 30972297, 2019). "Moreover, it has been reported that PDPN can mediate collective cell migration (CCM) to promote tumor invasion without EMT." (PMID 31217907, 2019). "However, the suppression of PDPN in such cells by siRNA did not affect the biological properties of tumor cells, which suggests that this glycoprotein is not directly responsible for their migration and invasiveness." (PMID 28938000, 2017). "From these reports, we hypothesized that high expression of podoplanin is important in tumour growth along with activation of platelets rather than the number of platelets." (PMID 28642617, 2017). "Interestingly, podoplanin is absent in tumor cells from several invasive adenocarcinomas such as breast, lung or pancreas." (PMID 28938000, 2017). "The expression level of LYVE–1 in tumor tissues of patients with lymph node involvement was similar with that in patients without lymph node involvement (P = 0.354), and the similar results were found for VEGFR–3 (P = 0.631), Podoplanin (P = 0.490), and Prox–1 (P = 0.503)." (PMID 29162097, 2017). "Both PDPN-expressing and non-expressing EXOs were able to stimulate blood vessel angiogenesis, a feature shared by EVs released from different types of tumor cells." (PMID 26893367, 2016). "Subsequent immunostaining of OSCC specimens demonstrated that PDGFRβ was abundantly expressed in stromal fibroblasts of all tested cases (12/12), while it was absent in tumor cells, with greater specificity than other known markers such as alpha smooth muscle actin or podoplanin (3/11)." (PMID 27128408, 2016). "In addition, other studies have shown that PDPN can stimulate collective tumor cell migration/invasion in the absence of EMT." (PMID 26893367, 2016). "The endogenous ligand of CLEC-2, podoplanin, could increase tumor cells motility by remodeling actin in the cytoskeleton and correlated with the onset of epithelial to mensenchymal transition (EMT), a key role in tumor metastasis." (PMID 27564117, 2016). "Considering these results, signaling via PDPN might not affect the factors involved in tumor formation in SCLC." (PMID 25909164, 2015). "The biological function of PDPN has not been fully defined, but the available data strongly suggest that it may play an important role as a mediator of tumor cell invasion." (PMID 24797369, 2014). "Although the function of PDPN in tumor biology, including cancer progression, is not yet clear our data might link podoplanin expression with metastatic potential of PTCs." (PMID 24797369, 2014). "Patients in the PDPN+ group had more frequent lymphatic invasion (P = 0.0461), vascular invasion (P = 0.0101), tumor size ≥3 cm (P = 0.0038), G3 grade tumor (P = 0.0344), and Union for International Cancer Control (UICC) grade pT3 or higher (P = 0.029) than patients in the PDPN– group." (PMID 24354864, 2013).
tumor (continued). "Interestingly, Podoplanin expression characterized both lymphatic vessels and tumor cells at the invasive front of control tumors, while no positivity was observed in treated tumors." (PMID 24185040, 2013). "Similarly, Notch1 expression in tumor cells was significantly correlated with lymph nodes metastasis (χ2 = 10.162, P = 0.001), LVD (χ2 = 6.362, P = 0.010), VEGF-C expression (χ2 = 17.176, P = 0.001), and podoplanin expression (χ2 = 6.877, P = 0.008)." (PMID 21939555, 2011). "In addition, tumour emboli within lymphatic spaces as well as metastatic cells from lymph nodes showed no podoplanin immunostaining in the vast majority of tumours, even in those cases with positive expression in the main tumour mass." (PMID 20196862, 2010). "Podoplanin/CLEC-2-dependent platelet stimulation by tumour cells promotes hematogenous tumour metastasis, possibly by inducing growth factor secretion by platelets and by promoting formation of a "platelet cap", which protects the tumour from mechanical forces." (PMID 20482880, 2010). "However, although most β-cell tumours did not undergo a cadherin switch in podoplanin-expressing Rip1Tag2 tumour cells, a subset of the tumours lost E-cadherin expression." (PMID 17179989, 2007). "Moreover, the functional consequences of PDPN targeting observed in our study, such as changes in immune cell infiltration or cytokine profiles, likely stem from the disruption of this critical CAF-mediated immunosuppressive axis, in addition to any direct effects on tumor cell signaling." (PMID 41573582, 2025). "Interestingly, increased podoplanin expression in CAFs is associated with peri-tumoral microvessels and LYVE-1 positive lymphatic vessels, though it does not correlate with VEGF-A or VEGF-D expression in tumor cells." (PMID 39404428, 2024). "Furthermore, chLpMab-7, a mouse-human chimeric anti-PDPN mAb with a different epitope than NZ-1, could not inhibit PDPN–CLEC-2 interaction but suppressed tumor growth and hematogenous metastasis to the lung in a neutralization-independent manner." (PMID 35159384, 2022). "Thus, podoplanin may help better stratify patients selected for elective neck node dissection in early tumor stages and clinically negative regional disease." (PMID 36247509, 2022). "Therefore, it was proposed that an LpMab-2 antibody would be an excellent tool for selectively targeting PDPN-positive cancer cells, inhibiting cancer-related thrombosis within tumor vessels, without interfering with normal cells that are located in lymphatic vessels." (PMID 34322381, 2021). "However, most studies are largely based on immunohistochemistry analysis and often do not define the cellular source of PDPN, which is important when considering the function of this protein as it can be expressed by tumor cells, CAFs, lymphatic endothelium, and some immune cells." (PMID 34879110, 2021). "However, recent studies have shown that oral SCC tumour cells induce the differentiation of CAFs through the production and release of TGF-β and, in turn, CAFs through the secretion of the same factor, which induces both the differentiation of new CAFs and the expression of PDPN in tumour cells." (PMID 31967978, 2020). "Interestingly, we observed co-localization of αSMA and podoplanin in the control fibroblasts (asterisks), not seen in the Fibro-ActA fibroblasts, suggesting differentiation to a myofibroblast lineage in the invasive tumor cultures." (PMID 27829391, 2016). "Moreover, the presence of podoplanin (D2-40) and vascular endothelial growth factor receptor-3 (VEGFR3) have been also confirmed by immunohis-tochemical staining, which are highly specific lymphatic endothelial markers and suggest that the tumor is more similar to a tumor of lymphatic origin." (PMID 24063649, 2013). "Taken together, these results point to PDPN expression in CRC as a negative prognostic factor and suggest its potential role in the tumor microenvironment." (PMID 40842027, 2025).